AFP (alpha fetoprotein)
Diseases named in the same sentence as AFP in open-access papers (continued):
Sharing a sentence is not in itself a finding about the gene and the disease.
tumor (continued). "The tumor characteristics, such as the tumor size (3.40 ± 2.00 for HA and 3.55 ± 1.61 for HT), tumor number, AFP level, presence of a tumor capsule, pathologic microvascular invasion, and histologic differentiation also were similar between the two groups." (PMID 32984060, 2020). "Another study showed that both clinical (consisting of patients age, AFP, HBsAg, and tumor size) and radiomic models performed poorly in predicting MVI (AUC of 0.734 and 0.783, respectively)." (PMID 32962762, 2020). "Among serum tumor markers, alpha-fetoprotein (AFP) is the most widely used serological marker for HCC evaluation." (PMID 33490235, 2020). "Alkaline phosphatase has resulted as independent factors for survival following DEB-TACE-1, together with tumor size and AFP." (PMID 32487071, 2020). "Age, race, American Joint Committee on Cancer stage, degree of tumour differentiation, tumour size, alpha-fetoprotein and tumour therapy were independent prognostic factors for survival in elderly HCC patients." (PMID 32117619, 2020). "All tested models included parameters for liver function (ie albumin, bilirubin, AST), most of them included tumour‐related parameters (ie AFP, tumour size, macrovascular invasion) and some included ‘other’ baseline parameters (age, HCC aetiology, ECOG PS)." (PMID 31579990, 2020). "The expression of CMTM6 was downregulated and was correlated with the AFP level and tumor metastasis of HCC patients." (PMID 32874775, 2020). "α-Fetoprotein (AFP) is often reported to be elevated in HCC patients accompanied with large tumor, early tumor recurrence, and vascular invasion." (PMID 32328093, 2020). "Univariate analysis found that in the LDR group, AFP, TB, HBV-DNA, and maximum tumor size were associated with OS (p=0.002, 0.041, 0.038, and 0.003, respectively)." (PMID 33425729, 2020). "The AFP model is based on tumor stage and AFP values, and assigns values to the diameter and number of nodules and AFP value." (PMID 32974380, 2020). "Factors with P < 0.10 including Child-Pugh class, BCLC stage, AFP, tumor size, metastasis, PVTT, and treatment were combined into the Cox proportional hazards regression model." (PMID 33521054, 2020). "Currently, the most commonly used methods of diagnosing HCC involve imaging or detection of tumor biomarkers, such as alpha-fetoprotein (AFP), from the patient’s serum." (PMID 32554864, 2020). "In the clinic, alpha-fetoprotein (AFP) is the main tumor biomarker available to guide the management of HCC; however, its low accuracy limits its usefulness as a screening test." (PMID 32295144, 2020). "This correlates with clinicopathological data which has shown marked similarity between type C cHCC-ICC and HCC with regards to male/female ratio, hepatitis infection, serum AFP levels and non-tumor liver histology." (PMID 33102226, 2020). "Tumor size, serum AFP, and ICG-15 were compared between HCC patients with and without microscopic VI." (PMID 32493393, 2020). "In combination of formate, AFP, and tumor size, the AUROC in predicting microscopic VI raised to 0.806 in the investigation group and 0.745 in the validation group." (PMID 32493393, 2020). "An interesting finding in our study is that the spectrum of tumor types that produce AFP according to literature matches tumor types with high AFP mRNA expression in TCGA dataset perfectly." (PMID 31897235, 2020). "Serum tumor markers (alpha fetoprotein, human chorionic gonadotropin, and lactate dehydrogenase) are prognostic factors and contribute to diagnosis and staging." (PMID 32102532, 2020). "AFP expression increased significantly (p ≤ 0.01) by 19-, 50- and 14-folds in first, second and third tumours, respectively, when compared to normal mice liver." (PMID 32203212, 2020). "We also found that low Aldob expression was significantly correlated with α-fetoprotein (AFP), albumin level, and tumor encapsulation." (PMID 33275593, 2020).
tumor (continued). "Some LCTs secrete T and/or E2, but tumor markers such as alpha-fetoprotein (AFP), human chorionic gonadotropin (hCG) and lactic acid dehydrogenase (LDH) are often negative." (PMID 32899084, 2020). "Multivariate analyses revealed that differentiation grade, alpha-fetoprotein, tumor size, and tumor extension were independent predictors of poor prognosis in patients with multifocal HCC." (PMID 32117759, 2020). "Protein expression was quantitated using the Image J software for those markers and showed that approximately 50% of tumour sections expressed AFP and CK19 while for GPC3 it was 20% and for CD44 it was 30%." (PMID 32203212, 2020). "Logistic regression of the risk factors for TACE refractoriness, including vascularization pattern, ALBI grade, AFP grade, γ-GT grade and major tumor size, was performed in the training cohort (n=412)." (PMID 32489476, 2020). "The mean level of AFP in the high group was higher than that in the low group (28-38.5 ng/ml vs 8-28 ng/ml), and the tumor in the high group was bigger than that in the low group (1.0-20.0 cm vs 0.7-5.2 cm)." (PMID 32963635, 2020). "MOGCTs can lead to elevations of tumor markers in the peripheral blood, including alpha-fetoprotein (AFP), beta-human chorionic gonadotropin (hCG) and lactate dehydrogenase (LDH)." (PMID 32485873, 2020). "In our study Preoperative bilirubin level, AFP >400 ng/ml, TTV, macro, and microvascular invasion were associated with tumor recurrence in the univariate analysis." (PMID 32426129, 2020). "Combining the two image features with clinical risk factors, such as age > 56.61 years, tumor size > 12.45 mm, having HCV, and ln(AFP) > 1.954, is practical and worthwhile for the early detection of small HCCs." (PMID 33193879, 2020). "We found that AST ≥119 IU/L, GGT ≥115 IU/L, Child–Pugh class C liver function, Cr ≥ 91 μmoI/L, AFP ≥400 ng/ml, and largest tumor diameter ≥5 cm were independent predictors of individual survival outcomes." (PMID 32149077, 2020). "The largest weighted parameter in the MoRAL-AI was tumor diameter, followed by alpha-fetoprotein, age, and protein induced by vitamin K absence-II." (PMID 33003306, 2020). "FPR combined with GPR possessed a larger area (0.943, 0.971) and sensitivity (87.50%, 89.81%) than FPR or GPR alone for differentiating AFP-NHCC with tumor size < 3 cm or at the BCLC-A stage." (PMID 32190001, 2020). "AFP is the most commonly applied tumour marker in HCC; however, its sensitivity varies (33–85%, mean: 56.3%), which is not optimal for early diagnosis of HCC38." (PMID 32782270, 2020). "Alpha-fetoprotein (AFP) is an established and routine tumor marker in patients with HCC, which is readily available for patients who were AFP-positive before LT." (PMID 32614912, 2020). "The number of SEPCs was correlated with the expression levels of HCC tumour markers α-fetoprotein (AFP) and CA199." (PMID 33312206, 2020). "For example, Kim and colleagues improved the performance of their radiomic model in predicting survival form a hazard ratio of 7.42 to 19.88 (p < 0.0001) by incorporating alpha-fetoprotein (AFP) levels, liver function status (Child-Pugh score) and tumor size." (PMID 32962762, 2020). "Biochemical examination revealed elevated serum α-fetoprotein (AFP) at 359 ng/mL, whereas the tumor markers CA-125, CA-199, and CEA were all within normal range." (PMID 32064359, 2020). "Independent risk factors of OS included Albumin-bilirubin (ALBI) grade, maximal tumor size, alpha-fetoprotein, and tumor response to initial TACE, which were used to develop a scoring system (“ASAR”)." (PMID 32487089, 2020). "Variables with P-values < 0.05 in univariate analysis were included in our logistic regression models including demographic factors (sex, age, and smoking history), inflammatory factors (CRP or ferritin), and tumor markers (CEA or AFP)." (PMID 33123542, 2020).
tumor (continued). "This impaired AIM2 expression was associated with higher alpha-fetoprotein (AFP) levels, vascular invasion, poor tumor differentiation and lymph node metastasis." (PMID 33613561, 2020). "The BCLC stage, largest tumor size, AFP, ALT and deep learning signature were identified as prognostic factors correlated to OS in the univariate analysis." (PMID 33102242, 2020). "A prognostic score by using positive tumor markers (alpha-fetoprotein (AFP), fucosylated AFP and des-gamma-carboxy prothrombin) showed a useful predictive prognostic value in HCC patients treated with transcatheter arterial chemoembolization." (PMID 32514252, 2020). "Elevated levels of AFP were known to be correlated with an increased tumor size and portal vein thrombi, as well as increased risks of liver transplant waitlist dropout and post-transplant recurrence." (PMID 32610709, 2020). "During the long-term follow-up after RFA for HCC, significantly negative effects on OS were found for age, prothrombin activity, advanced CTP grade, tumor size, tumor number, serum level of AFP, and the presence of porto-systemic collateral vessels." (PMID 32029840, 2020). "The levels of tumor markers before initial treatment were high; alpha-fetoprotein (AFP) level was 74.4 ng/mL (normal ≤ 13.4) and protein induced by the absence of vitamin K or antagonist-II (PIVKA-II) was 1204.58 mAU/mL (normal ≤ 40)." (PMID 33301055, 2020). "This analysis showed that mortality was associated with age < 70 years, ECOG PS = 2, Child-Pugh class B, multiple tumors, MVI or EHS, tumor size > 5cm, AFP > 200 ng/dL, bilirubin > 1.1 mg/dL, international normalized ratio (INR) > 1.25, and treatment." (PMID 32163475, 2020). "AFP is a tumor marker protein that can increase significantly in case of liver damage and certain other cancers." (PMID 32339207, 2020). "This research aimed to further show the utility of TA-AAbs as biomarkers of HCC and assess their use in combination with Alpha-fetoprotein (AFP) for detection of HCC across multiple tumor stages." (PMID 32374744, 2020). "Bai and co-authors revealed that the AFP level at diagnosis was an independent risk factor of tumor differentiation, TNM stage, tumor size, and survival of HCC patients through 78,743 HCC patients." (PMID 32426269, 2020). "Laboratory studies should be obtained, including tumor markers (alpha-fetoprotein (AFP), carcinoembryonic antigen (CEA), and cancer antigen 19-9 (Ca 19-9))." (PMID 33396821, 2020). "The secreted AFP can affect other adjacent cells by binding to their receptors, thus stimulating tumour cell biological behaviour." (PMID 33090723, 2020). "In this study, tumor size > 12.45 mm, having HCV, and ln(AFP) > 1.954 were independent risk factors for small HCCs in high-risk patients." (PMID 33193879, 2020). "The expression of ASNS has been reported to be high in HCC tumor tissues and closely correlated with the serum AFP level, tumor size, microscopic vascular invasion, tumor encapsulation, TNM stage, and BCLC stage." (PMID 32746792, 2020). "The AUC of Linc00152 was greater than those of any other circulating lncRNAs and the currently used tumor marker AFP, indicating remarkable efficacy of Linc00152 in predicting HCC from either benign liver diseases or healthy controls." (PMID 32733618, 2020). "AUC of the existed tumor markers including AFP, GPC-3 and TGFβ1 were 0.679, 0.879 and 0.577, respectively." (PMID 33282554, 2020). "High NAP1L1 expression in HCC tissues was associated with aggressive clinicopathologic features, such as serum AFP levels, tumor size and tumor number." (PMID 31516385, 2019). "Of examined tumor markers, serum AFP was elevated (48.3 ng/mL), while others including carcinoembryonic antigen were within a normal range." (PMID 31281709, 2019). "Tumor markers including alpha-fetoprotein (AFP), carcinoembryonic (CEA), carbohydrate antigens 199 (CA199), and carbohydrate antigens 125 (CA125) were also normal." (PMID 31590641, 2019).
tumor (continued). "In HCC, the AFP level depends not only on the status of the cellular origin but also on the tumor burden." (PMID 31676847, 2019). "AFP, as a typical tumor marker of GCTs, is related to the extent of the disease and can provide useful information for the diagnosis before operation." (PMID 31836006, 2019). "(A) AFP expression in control liver tissue, adjacent tissue < 1cm from tumor, tissue at operative site (> 1 cm from tumor or more), and tumor tissue for long-term and short-term survivors." (PMID 30886700, 2019). "Female white HCC patients aged 45‐64 years, with late AJCC stage, and with larger tumor size were more likely to have elevated AFP levels." (PMID 31517445, 2019). "A number of tumor antigens, such as human alpha-fetoprotein (AFP), GPC-3 and telomerase-reverse transcriptase (hTERT) have been identified as vaccine-based immunotherapeutic targets for HCC." (PMID 31500650, 2019). "Tumor size (p = 0.044), higher AFP model score (p = 0.019), prolonged graft ischemia (p = 0.016), and younger donor age (p = 0.041) were significant risk factors in patients with intrahepatic dissemination." (PMID 31163668, 2019). "With AFP as a single tumor marker for PHC diagnosis, it had a sensitivity of 63.3% with a specificity of 80.8%." (PMID 31205886, 2019). "Patients who had MDT management were older, and included a higher number of men, had more preserved liver function, less advanced tumor stage, lower levels of AFP and PIVKA-II levels." (PMID 30640924, 2019). "The current study suggests that elevated AFP, larger tumor size, stage 3 disease, low facility case volume, increased time interval from diagnosis to receiving SBRT, and low BED are associated with poor survival for unresectable HCC patients treated with SBRT." (PMID 30701703, 2019). "In GSE14520, there were five clinical factors affecting patients’ OS: TNM stage, tumor size, AFP concentration and multinodular characteristic; whereas the factors significantly associated with patients’ RFS were as follows: gender, TNM stage, and BCLC stage." (PMID 31434354, 2019). "Alpha-fetoprotein (AFP), an oncofetal glycoprotein normally expressed in fetus, is currently the most widely used tumor marker for HCC." (PMID 31635078, 2019). "Although AFP levels were higher in the female patients than in the male patients, most of the female patients had normal liver function, tumor sizes < 5 cm, and solitary tumors." (PMID 31413742, 2019). "Tumor bioluminescence as demonstrated by IVIS imaging correlates with serum AFP concentration with a correlation coefficient R2 of 0.92." (PMID 31636665, 2019). "hCG and AFP are produced by tumour cells, but an increased level of LDH in serum is a result of cell damage, as well." (PMID 31652641, 2019). "Elevated GLR value had poor overall survival (OS) and progression-free survival (PFS) of TS ≤ 5 cm HCC patients, GLR level and tumor size were closely related to the prognosis of small HCC patients compared with AFP." (PMID 31165038, 2019). "The patient who had complete response had AFP-peptide derived T-cell receptor induction against the tumor cells." (PMID 31366113, 2019). "It was previously reported that young adult HCC patients usually had a higher AFP level, larger tumor size and more frequent metastasis at diagnosis." (PMID 31295310, 2019). "In conclusion, a preoperative predictive risk score for early recurrence of HCC after LT was constructed using 3 variables (pre-LT AFP, largest tumor diameter, and the number of nodules)." (PMID 31752756, 2019).
tumor (continued). "Clinically, the overexpression of SOCS5 in HCC patients was significantly correlated with aggressive tumor features such as increased AFP level, large tumor size, vascular invasion, and advanced TNM stage." (PMID 31406106, 2019). "The multivariate analysis revealed that the age, tumor size, type of surgery and AFP level significantly affected OS." (PMID 30863723, 2019). "Diagnostic efficacy of a combination of miR-92a and AFP was powerful for HCC, in particular screening of early tumor and low-level AFP patients." (PMID 31640265, 2019). "The AFP promoter is a low-density CpG region that was found hypermethylated in the non-tumour-adjacent tissues and in low AFP tumours, but hypomethylated in AFP-high tumours (p < 0.001)." (PMID 31285588, 2019). "All routine laboratory investigations and tumor markers were within normal limits (alpha fetoprotein [AFP], cancer antigen 125 [CA125], CA 19-9, carcinoembryonic antigen [CEA], adrenocorticotropic hormone [ACTH])." (PMID 31440438, 2019). "The elevated expression of MCM7 was highly correlated with the tumor diameter, Edmondson–Steiner grading, survival time, portal venous emboli, and AFP concentration of HCC patients." (PMID 31186405, 2019). "The results also suggest that patients with HCC and a low preoperative LMR have more aggressive tumour behaviour, including a larger tumour size and higher serum AFP concentration, than patients with a high preoperative LMR." (PMID 31388642, 2019). "The results of the multivariate analysis showed that AFP that decreased by less than 60% and tumour size that decreased by less than 50% after neoadjuvant chemotherapy were significant independent prognostic risk factors." (PMID 31822277, 2019). "A significant correlation between primary tumour size and the extent of AFP and bHCG elevation was reported in a small Spanish study in 1984, but no further systematic evaluations of this issue have been reported to date." (PMID 31275973, 2019). "Other clinical factors were analysed retrospectively, including the surgical strategy, initial serum AFP value and tumour size at the beginning of therapy." (PMID 31822277, 2019). "Then, the results of AFP levels in HCC tumors and paired para-carcinoma normal tissues showed significantly higher AFP in HCC tumor tissues." (PMID 31581132, 2019). "The median alpha-fetoprotein level was 13 IU/mL and tumor differentiation was assessed as G1 in 23.5% of patients, G2 in 65.5% of patients, and G3 in 11% of patients." (PMID 31618968, 2019). "The rarity of this tumor makes it difficult to endorse the sensitivity of AFP and PIVKA-II as a screening test for pure pancreatic HC." (PMID 31784920, 2019). "For comparison, AFP values for different tumour sizes or differentiation status or liver function were also analysed." (PMID 30341783, 2019). "Consistent with the results of bioinformatics analysis, patients with high AFP level, advanced tumor stage, and poor tumor differentiation had lower CTC‐297N7.9 expression level in their tumor tissues." (PMID 31674731, 2019). "Univariable analyses showed that mean tumor size, total bilirubin, AFP > 400 ng/mL, BCLC B and therapy method (TACE-RFA) were related to OS." (PMID 31640620, 2019). "Altered circRNAs expression was significantly associated with tumor stage, differentiation, size, numbers, vascular invasion, organ metastasis, and AFP (alpha-fetoprotein) in almost studies." (PMID 31187026, 2019). "AFP ≥ 400 ng/ml, tumor size ≥5 cm, tumor number ≥2, macro- and microvascular invasion, distant metastasis and positive margin were risk factors for both DFS and OS for the PLC patients." (PMID 31567946, 2019). "The conventional tumor markers AFP, hCG, and LDH have demonstrated value in the clinical management of testicular malignant TGCT." (PMID 31354629, 2019). "In our series, tumor markers (AFP level >200 ng/ml) and corona enhancement were independent predictors in the postoperative prediction model according to multivariate analysis." (PMID 31850221, 2019).